IGF2BP3 (insulin like growth factor 2 mRNA binding protein 3)
Diseases named in the same sentence as IGF2BP3 in open-access papers (continued):
Sharing a sentence is not in itself a finding about the gene and the disease.
tumor (continued). "Taken together, our current study identified a critical role for IGF2BP3 and m6A modification in tumor invasion and subsequent metastasis." (PMID 41285728, 2025). "The upregulation of IGF2BP3 expression in tumor tissues across all four cancer types, as well as in their adjacent normal tissues, was further substantiated by IHC analysis." (PMID 40765570, 2025). "In conclusion, our study highlights the potential of IGF2BP3 as a prognostic biomarker for MCC and provides insights into the mechanisms underlying tumor progression." (PMID 40162116, 2025). "Analysis of TCGA-LUAD data revealed that elevated IGF2BP3 expression correlates with advanced tumor stages and poor patient survival, consistent with its established role in stabilizing pro-survival transcripts such as c-MYC and CD44." (PMID 40313617, 2025). "We observed that CDKN2B-AS1, IGF2BP3, and hsa-miR-497-5p exhibited good prognostic abilities in subgroups such as Primary therapy outcome CR, Residual tumor R0, Post-Menopause, and Hormone therapy NO." (PMID 39883704, 2025). "Studies have found that METTL3 upregulates the m6A level of heparin binding growth factor (HDGF) mRNA, and then enhances its stability and promotes its expression through IGF2BP3, thereby increasing tumor angiogenesis and promoting gastric cancer metastasis." (PMID 40356596, 2025). "The data show a clear and meaningful link between higher IGF2BP3 levels and more advanced tumor grades, later clinical stages, and increased lymph node metastasis in individuals with LUAD." (PMID 40801655, 2025). "To further verify the importance of IGF2BP3 in tumor metastasis, we examined its levels in primary tumors and corresponding lung metastases in an MCC xenograft mouse model established from MCPyV-positive WaGa cells." (PMID 40162116, 2025). "IHC imaging and scoring revealed that IGF2BP3 expression was significantly higher in 74 CRC tissues compared to 24 adjacent non-tumor tissues." (PMID 40765816, 2025). "The simultaneous high expression of IGF2BP3 and OLFML1 is associated with poor prognosis in CRC patients, as it promotes stemness, tumor growth, and progression." (PMID 40765816, 2025). "In tumor cells, lactate accumulation induces IGF2BP3 lactylation and enhances m6A methylation of PCK2 and NRF2 mRNAs, reprogramming serine metabolism." (PMID 40165895, 2025). "The results showed that the tumor volume and weight were significantly reduced in the IGF2BP3 knockdown group (shIGF2BP3) compared with the normal saline control group (shNC)." (PMID 40083693, 2025). "IGF2BP3 promotes tumor cell growth and viability by binding to the 3′UTR of target mRNAs, thereby enhancing their stability and translational efficiency." (PMID 40801655, 2025). "At the same time, after cisplatin administration, the tumor volume and weight of nude mice in IGF2BP3 knockdown group decreased compared with the normal saline control group." (PMID 40083693, 2025). "Zhao observed that overexpression of IGF2BP3 can promote cell proliferation, tumour migration and invasion in vitro, while low expression of IGF2BP3 has the opposite effect, and IGF2BP3 can promote tumour metastasis in vivo." (PMID 38358034, 2024). "Our findings suggest a latent mechanism by which IGF2BP3 facilitates tumor development, and circ_0053943 enhances this function in UM." (PMID 38686044, 2024). "Subsequently, we investigated the role of IGF2BP3 in the immune infiltration and immune checkpoints of the tumor microenvironment in pan-cancer." (PMID 38577615, 2024). "Our findings, combined with these previous studies, showed that HMGB1 is an important intermediate molecule of IGF2BP3 induced tumor EMT and invasion/metastasis." (PMID 38504159, 2024). "Results showed that knockdown of IGF2BP3 markedly reduced the tumor volumes and weights of xenografts in nude mice, suggesting IGF2BP3 plays an oncogenic role in GC progression in vivo." (PMID 38448411, 2024).
tumor (continued). "The results of qPCR showed that METTL3 and IGF2BP3 were significantly overexpressed in the tumor cells, while YTHDC2 was significantly downregulated (p < 0.05)." (PMID 39717046, 2024). "This suggests that copy number gain/amplification contribute to IGF2BP3 upregulation in a wide-variety of tumor." (PMID 38504159, 2024). "Statistical data demonstrated that IGF2BP3 was in positive connection with tumor lymph node, grade and stage of CC sufferers." (PMID 38355626, 2024). "Importantly, this upregulation of IGF2BP3 has been associated with the regulation of both total and membrane-bound expression levels of programmed cell death ligand 1 (PD-L1), which has been established to be associated with immune suppression and tumor progression." (PMID 39342406, 2024). "In this project, MYO16-AS1 was found to inhibit HK2 mRNA degradation through competitive binding with IGF2BP3 protein in the cytoplasm, inhibiting tumor progression both in vitro and in vivo." (PMID 38041756, 2024). "Consistently, RT-qPCR and western blot assays revealed that expressions of IGF2BP3 were also significantly elevated in GC tumor tissues compared to para-tumor tissues." (PMID 38448411, 2024). "IGF2BP3 knockdown inhibited, while IGF2BP3 overexpression promoted the proliferation of tumor cells." (PMID 38992083, 2024). "To assess the expression profiles of IGF2BP3, we analyzed its expression levels in 33 different types of tumor and normal tissues through integrated data from TCGA and GTEx databases." (PMID 38504159, 2024). "IGF2BP3 influences tumor angiogenesis by modulating different targets in various digestive system cancers." (PMID 39295872, 2024). "The results demonstrated that IGF2BP3 was involved in all signaling pathways except the tumor inflammation signature, ECM related genes, and angiogenesis related pathways." (PMID 38577615, 2024). "Accordingly, high expression of IGF2BP3 has been detected in some precancerous human diseases, such as abnormal hyperplasia in Barrett's oesophagus and tumours in the pancreas." (PMID 38358034, 2024). "High IGF2BP3 expression was significantly correlated with the advanced pathological stages and tumor grades." (PMID 38992083, 2024). "Specifically, IGF2BP3-positive extracellular vesicles sustained the migration and invasive potential of recipient tumor cells as well as the expression of IGF1R and the downstream AKT pathway." (PMID 38892104, 2024). "In this study, we investigated the role of SRD5A3 and IGF2BP3 during bladder tumorigenesis and tumor cells resistant to CDDP." (PMID 39680264, 2024). "For example, in GC, IGF2BP3 enhances tumor angiogenesis and cell migration by promoting HIF1A expression." (PMID 39295872, 2024). "The oncogenic role of IGF2BP3 in tumorigenesis and tumor progression has been reported by previous studies, confirming our observations of IGF2BP3’s correlation with a poor prognosis in mCRPC patients." (PMID 38610981, 2024). "Collectively, these findings provide strong evidence that the effects of BET inhibitors on NETosis and tumor survival inhibition result, in part, from the downregulation of IGF2BP3 and subsequent decrease in CSF3 expression." (PMID 38167409, 2024). "In this paper, a comprehensive bioinformatics analysis of IGF2BP3 in HCC was performed by using the tumor and normal tissue data from TCGA and GETx databases." (PMID 38577615, 2024). "We also revealed the distribution of IGF2BP3 in the tumor microenvironment, some of IGF2BP3 existed in CD8Tex cells, which provided some new evidence for immune modulation." (PMID 38577615, 2024). "Next, IHC staining of mouse tumor tissue using the SCD antibody showed that SCD expression diminished following IGF2BP3 knockdown." (PMID 38355626, 2024). "Our results further indicated that enforced IGF2BP3 expression significantly reduced the ability of BET inhibitors to reduce tumor survival, extend survival time, and inhibit NETosis." (PMID 38167409, 2024).
tumor (continued). "In addition, tumor cells with high circNEIL3 expression drove macrophage infiltration into the tumor microenvironment via delivering exosomes containing circNEIL-3 to tumor-associated macrophages (TAMs) and then acquired immunosuppressive properties via IGF2BP3." (PMID 38075205, 2024). "After predicting the potential of IGF2BP3 transcription factors, we found several factors that were highly expressed in tumour tissue RNA‐Seq." (PMID 38358034, 2024). "Considering that the mechanisms of drug action for HKDC1 and IGF2BP3 differ significantly, the potential of drugs targeting both is likely to be more efficient than targeting independent mechanisms in the tumor cell." (PMID 39164728, 2024). "Knocking down IGF2BP3 significantly inhibited the expression of PD-L1, which cooperates with tumor cells to escape immune surveillance." (PMID 39054967, 2024). "Our study highlights the importance of post-transcriptional regulation in AEG tumor progression and the clinical significance of the m6A/IGF2BP3/CDC25A axis in AEG." (PMID 39247830, 2024). "In conclusion, our study highlights the role of post-transcriptional regulation in modulating AEG tumor progression and elucidates the functional importance of the m6A/IGF2BP3/CDC25A axis in AEG cells." (PMID 39247830, 2024). "The level of IGF2BP3 in hepatocellular carcinoma tumour‐initiating stem cells was higher than that in all tumour cells." (PMID 38358034, 2024). "Treatment with IGF2BP3 RNA decoy oligonucleotides caused isoform switching of PIP4K2A‐S to PIP4K2A‐L and suppressed the expression of p85 and p‐AKT, which inhibited tumor growth and metastasis both in vitro and in vivo." (PMID 38059827, 2024). "The clinical significance of IGF2BP3 was evaluated using tumor related databases and clinical tissues." (PMID 38448411, 2024). "After adjusting for clinical variables, including age, sex, tumor grade, pathological stage, and T stage, univariate (P < 0.001) and multivariate (P < 0.05) Cox analyses showed that IGF2BP3 was an independent predictor of overall survival." (PMID 38992083, 2024). "In numerous tumour‐related studies, scholars have found that IGF2BP3 promotes the occurrence and development of tumours." (PMID 38358034, 2024). "The positive correlation between the expression of IGF2BP3 and higher tumor grade was observed in multiple other cancer types." (PMID 38429265, 2024). "Vein tail tumour injection assays were applied to show that IGF2BP3 knockdown diminished pulmonary metastasis while overexpression of circRARS facilitated pulmonary metastasis." (PMID 38073586, 2023). "The TCGA database was used to identify expression patterns of IGF2BPs and showed that in PTC tumor samples IGF2BP3 were expressed in low levels while IGFBP2 was highly expressed, IGF2BP1 has barely any difference, compared to normal samples." (PMID 38092752, 2023). "The main aim of this study was to provide visualization of the systemic prognostic landscape of IGF2BP3 in pan-cancer and to uncover the potential relationship between IGF2BP3 expression in the tumor microenvironment and immune infiltration profile." (PMID 36761737, 2023). "The positive feedback feature in GSCs mediated by the interaction among circRNF10, ZBTB48, with IGF2BP3 was morphologically identified by immunohistochemical staining of orthotopic xenograft tumor specimens." (PMID 37723588, 2023). "Intriguingly, IGF2BP3 was regarded as an RNA-binding proteins (RBPs), for which several clinical trials have emerged recently to evaluate the anti-tumor efficacy of specific antisense oligonucleotide (ASO)." (PMID 37853162, 2023). "IGF2BP3, recently identified as a novel m6A reader, has been found elevated in various cancers and involved in the tumorigenesis and tumor progression." (PMID 37853162, 2023).
tumor (continued). "The expression of IGF2BP3 at the mRNA and protein levels was attenuated by knockdown of linc01224, which indicated that downregulation of linc01224 inhibited tumor-promoting activity in HSCC by repressing IGF2BP3 protein synthesis." (PMID 37859812, 2023). "IGF2BP3 was highly expressed in ccRCC and acted as an m6A reader, exerting tumor-promoting effects by enhancing mRNA stability and translation." (PMID 37175461, 2023). "Researchers should focus more on the close relationship between IGF2BP3 and the tumor microenvironment." (PMID 37298373, 2023). "IGF2BP3 is upregulated and potentially oncogenic in various tumor types, such as bladder cancer, lung cancer, gastric cancer, and so forth." (PMID 37658049, 2023). "Next, we performed immunohistochemistry assays to detect the effects of IGF2BP3/circGNB1/miR-515-5p/miR-582-3p/XPR1/IL6 axis on tumor tissues." (PMID 37407973, 2023). "In summary, our research is the first to provide evidence that linc01224 acts as a novel tumor promoter through the miR-485-5p/IGF2BP3 axis in HSCC." (PMID 37859812, 2023). "As a binding protein of the same type, IGF2BP1, IGF2BP2 and IGF2BP3 interact with same LncRNAs in the same tumor and has the same function." (PMID 37365581, 2023). "IGF2BP3 was considered as an m6A reader and contributed to tumor progression through mediating the stabilization of IGF2BP3 targets in an m6A-dependent manner." (PMID 36639675, 2023). "We must deeply study the mechanism of action of IGF2BP3 and strive to develop its potential in targeted tumor therapy." (PMID 37298373, 2023). "We measured the expression levels of miR-2110, ENO2, and IGF2BP3 in tissues, and compared to tumor adjacent tissues, the expression of miR-2110 was decreased; while, ENO2 and IGF2BP3 were upregulated in cancer tissues." (PMID 37644235, 2023). "IGF2BP3 expression increases with tumour grade and correlates with shorter OS.YTHDC2 and IGF2BP3 are negative and positive prognostic factors for OS." (PMID 36831575, 2023). "In hepatocellular carcinoma, lnc-CTHCC, stabilized by METTL3/IGF2BP1/IGF2BP3 via m6A modification, promotes tumor initiation and development by binding hnRNPK and activating YAP1 transcription." (PMID 37280679, 2023). "In this study, we analyzed gene expression data of IGF2BP3 from The Cancer Genome Atlas (TCGA), Gene Expression Omnibus (GEO), and Genotype-Tissue Expression databases to compare IGF2BP3 expressions in the tumor and normal tissues." (PMID 36732736, 2023). "Increasing evidence has indicated that IGF2BP3 is highly expressed and promotes tumor progression in NSCLC, however, the molecular mechanism of IGF2BP3 in NSCLC has not been elucidated." (PMID 36639675, 2023). "CircTNPO3 inhibited tumor metastasis via decoying IGF2BP3 protein and regulating the expression of Snail and Myc in gastric cancer." (PMID 38152652, 2023). "HeLa‐Parkin cells expressing wild‐type IGF2BP3 formed a large number of tumour spheroids, but it was hardly observed in mutant IGF2BP3‐expressing cells." (PMID 37877353, 2023). "The expression of IGF2BP3 is increased in multiple tumors, suggesting that IGF2BP3 plays the role of a tumor-promoting factor." (PMID 37298373, 2023). "And the expression of IGF2BP3 was significantly correlated with tumor purity (cor=0.094, P=4.03e-02) and CD4+ T cells (cor=0.19, P=2.07e-05)." (PMID 36793593, 2023). "Overall, an inverse correlation was noted between tumor purity and the expression levels of IGF2BP3, EMP3, TUBA1C, AK2 and IGFBP2 (average PCC = −0.48)." (PMID 38171932, 2023). "Four weeks later, tumour volume and weights in the IGF2BP3 knockdown group were both lower than those in the control, which indicates that knockdown of IGF2BP3 inhibited tumour proliferation in vivo." (PMID 37743642, 2023). "IGF2BP3 overexpression promoted, while IGF2BP3 downregulation inhibited tumor metastasis and the stemness phenotype of NPC cells in vitro and in vivo." (PMID 37853162, 2023).
tumor (continued). "IGF2BPs, generally including IGF2BP1, IGF2BP2 and IGF2BP3, have also been identified as m6A methyl-binding proteins and they are involved in the stability and degradation of various LncRNAs during the tumor occurrence and development." (PMID 37365581, 2023). "Together, these data suggest a prognostic association with IGF2BP3 expression in STS, specifically implicating its role in oncogenesis and tumor progression for DD LPS." (PMID 37760460, 2023). "The results were further verified in xenograft mouse models, in which the ability of cetuximab to reduce tumor growth rate and volume was hindered by the overexpression of IGF2BP3 and promoted by the downregulation of IGF2BP3." (PMID 37658049, 2023). "The IGF2BP3 wild‐type and mutant groups displayed a significant difference in tumour volume and weight with time, indicating decreased tumourigenesis with IGF2BP3 mutation." (PMID 37877353, 2023). "The application of this signature correctly clustered tumor samples according to their expression of IGF2BP3, confirming its value in the clinical setting." (PMID 37353558, 2023). "To further compare IGF2BP3 expression between the tumor and normal tissues, we combined data from TCGA and GTEx." (PMID 36761737, 2023). "By contrast, IGF2BP3 silencing significantly decreased the number of disseminated tumor nodules in the lungs." (PMID 37853162, 2023). "Inhibiting the IGF2BP3/MCM5/NICD1 axis impairs the tumor cell plasticity and potently abrogates distant metastasis of LUAD cells." (PMID 37171793, 2023). "Mechanistically, circITGB6 promotes tumor metastasis through its direct interaction with IGF2BP3, leading to activation of IGF2BP3 and consequent stabilization of its downstream transcript, PDPN mRNA." (PMID 37898647, 2023). "CircTNPO3 suppressed tumor metastasis via interaction with IGF2BP3 and destabilization of SERPINH1 mRNA in clear cell renal cell carcinoma." (PMID 38152652, 2023). "In the future, it is necessary to prospectively study the expression of IGF2BP3 and its significance in cancer immune infiltration, and to develop new drugs with higher anti-tumor activity targeting IGF2BP3." (PMID 36761737, 2023). "Subcutaneous tumor xenografts formed by IGF2BP3‐overexpressing A549 cells displayed penetration of tumor cells into neighboring subcutaneous tissue, which was barely observed in the similarly sized tumor xenografts formed by vector‐control A549 cells." (PMID 37171793, 2023). "After resection of the lungs at 6 weeks after injection, more tumor nodes were found on lung surfaces of mice in the IGF2BP3 overexpression group, compared with those in the control group." (PMID 37853162, 2023). "In xenograft models, the tumour volume increased more slowly in the IGF2BP3 knockdown group than in the control." (PMID 37743642, 2023). "Conversely, the IGF2BP3-silenced cells presented lower tumor incidence and slower xenograft outgrowth." (PMID 37853162, 2023). "The expression of IGF2BP3 was significantly positively correlated with tumor purity and CD4+T cells." (PMID 36793593, 2023). "Insulin-like growth factor 2 mRNA-binding protein 3 (IGF2BP3) has been reported to exhibit an oncogenic effect as an RNA-binding protein (RBP) by promoting tumor cell proliferation, migration and invasion in several tumor types." (PMID 36761737, 2023). "Recently, studies about IGF2BP3 showed the connection between the immunohistochemical evaluation of IGF2BP3 expression and tumor growth and prognosis." (PMID 36450891, 2023). "The growth curve of the xenograft tumors showed that overexpression of IGF2BP3 accelerated tumor growth, and there were significant differences in the xenograft weights after excision." (PMID 35217832, 2022). "This suggests a molecular basis for the implication of IMP-1 and its close paralog, IGF2BP3, in the drug resistance of tumor cells." (PMID 35104504, 2022).